FUT1 (fucosyltransferase 1 (H blood group))
Diseases named in the same sentence as FUT1 in open-access papers (continued):
Sharing a sentence is not in itself a finding about the gene and the disease.
rheumatoid arthritis (3 papers, 2014 to 2024). A chronic, systemic autoimmune disorder characterized by inflammation in the synovial membranes and articular surfaces. "A previous study revealed that FUT1 was robustly expressed and responsible for inflammatory injury in the synovial tissues of rheumatoid arthritis patients." (PMID 38934781, 2024).
atopic dermatitis (2 papers, 2024). "A recent study also reported that the expression of FUT1 and H2 antigen is reduced in the granular layers of the atopic dermatitis skin." (PMID 39420441, 2024).
cholangiocarcinoma (2 papers, 2019 to 2023). A carcinoma that arises from the intrahepatic biliary tree (intrahepatic cholangiocarcinoma) or from the junction, or adjacent to the junction, of the right and left hepatic ducts (hilar cholangiocarcinoma). "In this study, the clinical relevance and significance of terminal fucose (TFG), by fucosyltransferase-1 (FUT1) in carcinogenesis and progression of cholangiocarcinoma (CCA) were demonstrated." (PMID 31754244, 2019).
E. coli infection (2 papers, 2019 to 2025). "The objective of this study was to evaluate genetic resistance of the polymorphism at nucleotide 307 (M307) in the FUT1 gene, to F18 E. coli infection considering different genotypes." (PMID 39917050, 2025). "In addition, resistance to F18+ E. coli infection has been associated with multiple genetic loci including FUT1, FUT2, ST3GAL1, and B3GALNT." (PMID 39917050, 2025). "Prof. Cox’s group is currently analysing data to suggest the genetic regulation of FUT2 (a gene closely related to FUT1), might also be controlling blood group A and O blood expression in the pigs small intestine, and thus piglet susceptibility to F18+ E. coli infection." (PMID 30709726, 2019). "Recent genetic studies have further identified that piglet susceptibility to F18+ E. coli infection might not be an absolute correlate with the FUT1 M307 related SNP." (PMID 30709726, 2019).
pancreatic cancer (2 papers, 2019 to 2020). "The expression of FUT1 is decreased in pancreatic primary tumor cell lines compared to normal tissue, but the ectopic re-expression of FUT1 in the metastatic pancreatic cancer cells inhibits metastasis by enhancing the cell surface abundance of Ley and inhibiting E-selectin-mediated adhesion." (PMID 31450600, 2019).
benign meningioma (1 paper, 2024). A grade I, slowly growing meningioma. "However, the gene expression experiments demonstrated that FUT1 and FUT8 were highly expressed in the malignant meningioma—HKBMM—vs the primary benign meningiomas—SUT-MG12 and SUT-MG14." (PMID 38274327, 2024).
cervical cancer (1 paper, 2025). A primary or metastatic malignant neoplasm involving the cervix. "FUT1 amplification was the most common genomic alteration, with the highest alteration frequency observed in cervical cancer." (PMID 40084262, 2025).
Corneal opacity (1 paper, 2020). A reduction of corneal clarity. "Together, these data demonstrate that FUT1 deficiency induces immune dysregulation in the ocular surface and corneal opacity in steady state and under desiccating stress." (PMID 32332708, 2020).
COVID-19 (1 paper, 2022). A disease caused by infection with severe acute respiratory syndrome coronavirus 2. "The D-test shows that FUT1 is located in the left-tail under C10AA (pD ≃ 9.8 × 10−4), and therefore this gene’s variations may be a possible risk factor for severe COVID-19." (PMID 36156592, 2022).
diarrhoea (1 paper, 2018). "Further study on host FUT1 genotype are desirable to improve the knowledge on the relationship between FUT1 genotype, the mucosal bacterial community, and the host immune response in order to elucidate the perspective of e.g. breeding strategies on gut health parameters others than diarrhoea." (PMID 30148866, 2018).
eyelid inflammation (1 paper, 2022). "Since SOD1 attenuates ocular inflammation by scavenging ROS, a lower level of SOD1 in Fut1 KO mice might lead to eyelid inflammation and MGD." (PMID 36012728, 2022).
meningioma (1 paper, 2024). A generally slow growing tumor attached to the dura mater. "High expression of FUT1, FUT2, FUT3, FUT6, FUT7, and FUT8 in malignant meningioma cell lines—HKBMM and IOMM-Lee—may represent a fucosylation signature of mucin-type O-linked glycosylation in malignant meningiomas." (PMID 38274327, 2024). "FUT1, FUT2, FUT3, FUT6, FUT7, and FUT8 were highly increased in malignant meningioma cell lines." (PMID 38274327, 2024).
nasopharyngeal carcinoma (1 paper, 2022). A carcinoma arising from the nasopharyngeal epithelium. "Gene expression profiling analysis unexpectedly showed a significant number of up- and down-regulated metabolism-associated FUT1 genes in nasopharyngeal carcinoma." (PMID 35462848, 2022).
ovarian tumor (1 paper, 2023). "We observed 24 ABH antigen synthesis‐related genes in which five genes (FUT1, FUT2, FUT3, B3GNT3, and B3GNT2) were up‐regulated and three genes (ST3GAL3, ST3GAL4, and B3GALT2) were down‐regulated in ovarian tumor tissue versus adjacent tissues in all samples." (PMID 36415180, 2023).
renal fibrosis (1 paper, 2023). A final common manifestation of a wide variety of chronic kidney diseases characterized by glomerulosclerosis and tubulointerstitial fibrosis. "Together, these present results suggest that FUT1-mediated terminal fucosylation deteriorates renal fibrosis both in vitro and in vivo." (PMID 37085770, 2023). "Then, we further confirmed the level of terminal fucosylation by UEA-I staining and FUT1 expression in unilateral ureteral obstruction (UUO)-induced renal fibrosis mice." (PMID 37085770, 2023). "The development of kidney fibrosis is attributed to FUT1-mediated terminal fucosylation, shedding light on the inhibition of terminal fucosylation as a potential therapeutic treatment against renal fibrosis." (PMID 37085770, 2023). "Here, we found that the expression of FUT1 significantly increased during renal fibrosis." (PMID 37085770, 2023). "Therefore, we applied a widely-accepted mice renal fibrosis model (UUO) to validate expression of FUT1." (PMID 37085770, 2023). "In summary, these in vitro results reveal that FUT1-mediated terminal fucosylation could promote renal fibrosis via EMT process." (PMID 37085770, 2023). "In this study, we first observed FUT1-mediated terminal fucosylation was upregulated in CKD and renal fibrosis." (PMID 37085770, 2023). "As EMT plays a pivotal role in the pathogenesis of renal fibrosis, we next assessed the expression of EMT-related molecules and found that FUT1 over-expression with TGF-β1 treatment could significantly increase EMT process in HK-2 cells." (PMID 37085770, 2023). "Furthermore, single FUT1 over-expression mildly elevated fibrosis-related molecules expression, while in combination with TGF-β1 could notedly promote renal fibrosis in HK-2 cells." (PMID 37085770, 2023).
tumor (55 papers, 1981 to 2025). "We examined the associations between FUT1 expression and DNA methylation, immune cell infiltration, tumor mutational burden (TMB), microsatellite instability (MSI), and patient prognosis." (PMID 40084262, 2025). "Our findings demonstrate significant associations between FUT1 expression, clinical prognosis, and DNA methylation, highlighting its potential as a stand-alone prognostic biomarker in multiple tumor types." (PMID 40084262, 2025). "Among these tumor associated glycans, the terminal alpha 1, 2-linked fucose of Lewisy and Globo H are synthesized by alpha 1, 2 fucosyltransferase, FUT1 and FUT2, in human." (PMID 30854233, 2019). "These associations suggest that FUT1 might influence tumor immunogenicity and predict responses to immune checkpoint blockade (ICB) therapy." (PMID 40084262, 2025). "To explore whether FUT1 expression influences the tumor microenvironment (TME), we analyzed its association with stromal and immune cell components." (PMID 40084262, 2025). "To explore the potential reasons for the differential FUT1 mRNA expression levels between tumor and adjacent normal tissues in various cancers, we further investigated the impact of DNA methylation and RNA modification patterns on FUT1 expression." (PMID 40084262, 2025). "FUT1, a rate-limiting enzyme in Lewis y antigen synthesis, plays a crucial role in tumor progression." (PMID 40084262, 2025). "Our findings demonstrate that FUT1 serves as a predictive biomarker in multiple malignancies, strongly correlating with tumor progression and patient prognosis." (PMID 40084262, 2025). "Experimental validation confirmed the role of FUT1 in promoting tumor cell invasion, migration, and proliferation." (PMID 40084262, 2025). "In LUAD, FUT1 expression was lower in tumor tissues compared to normal tissues, with high expression linked to better outcomes." (PMID 40084262, 2025). "During tumorigenesis, FUT1 promotes tumor stemness, adhesion, migration, and drug resistance through the AKT/mTOR/4EBP1 signaling pathway." (PMID 40084262, 2025). "We analyzed the correlation between FUT1 expression levels and the functional state scores of these 14 tumor cell pathways." (PMID 40084262, 2025). "This study provides the first comprehensive pan-cancer analysis of FUT1, revealing its variable expression across tumor and normal tissues." (PMID 40084262, 2025). "Further analysis of paired tumor and adjacent normal tissues from the TCGA database revealed that FUT1 mRNA expression was generally higher in tumor tissues across most cancer types compared to adjacent normal tissues." (PMID 40084262, 2025). "This study represents the first comprehensive pan-cancer analysis of FUT1, revealing its differential expression across tumor types and its prognostic significance." (PMID 40084262, 2025). "Studies suggest that glucose deprivation induces abnormal fucosylation of membrane glycoproteins mediated by FUT1, thereby sustaining tumor cell stemness through the AKT/mTOR/4E-BP1 signaling pathway." (PMID 38230205, 2024). "FUT1 was considered as a potential tumor suppressor, its abnormal expression was frequently found in various cancers." (PMID 33639954, 2021). "This was consistent with greater tumor mass in lungs as reflected by weight in mice injected with FUT1 and FUT2 overexpressing cells than that in vector control cells." (PMID 30854233, 2019). "Meanwhile, in the nude mouse transplantation model, CD147 and Beclin 1 protein was also increased in tumor cells transfected with FUT1 as compared to untransfected cells." (PMID 27863372, 2016). "A few studies have shown the involvement of FUT1 substrates in tumor cell proliferation and migration." (PMID 27560716, 2016). "Furthermore, FUT1 was linked to TME components, particularly stromal and immune scores, across multiple cancers, supporting its role in immune cell infiltration and tumor progression." (PMID 40084262, 2025).
tumor (continued). "Notably, the methylation levels of CpG-shores were higher in tumor tissues, with the overall methylation level of FUT1 in LIHC tumor tissues being higher than in adjacent normal tissues." (PMID 40084262, 2025). "This link may offer valuable insights into how FUT1 influences tumor biology, with potential implications for therapeutic strategies targeting glycosylation pathways in cancer." (PMID 40084262, 2025). "While FUT1 also exhibits associations with immune-related features such as TMB, MSI, and tumor-infiltrating immune cells, these results suggest its role in immune modulation may be secondary to its primary functions in tumor progression." (PMID 40084262, 2025). "While FUT1 is known to enhance tumor stemness, adhesion, migration, and drug resistance in specific cancers, its role across diverse cancer types and its association with clinical prognosis and molecular features remain unclear." (PMID 40084262, 2025). "Additionally, FUT1 plays an important role in a regulatory mechanism involving fucosylation through which glucose restriction promotes cancer stemness to drive tumor recurrence and drug resistance." (PMID 35462848, 2022). "Notably, multivariable analyses showed that a combination of high expression of FUT1 and B3TALT5 is an independent risk factor for recurrence and OS, in addition to vascular invasion and tumor size greater than 5 cm." (PMID 28883415, 2017). "Besides FUT1, we also showed high expression of B3GALT5 in HCC tissues to be associated with advanced TNM stage, metastasis, vascular invasion and tumor recurrence." (PMID 28883415, 2017). "In addition, we established a nude mouse transplantation tumor model, transplanting untransfected cells as well as FUT1-transfected cells and then determined changes in expression of the Lewis x and Lewis y antigens using immunohistochemistry." (PMID 27863372, 2016). "Given the inhibitory effects of autophagy on cell proliferation and tumor development, our work not only provide an alternative mechanism of FUT1-mediated tumorigenesis but also a new perspective on the interplay among α1,2-fucosylation, autophagy and tumorigenesis." (PMID 27560716, 2016). "Correlation analysis between FUT1 mRNA expression levels and various genomic instability scores, including aneuploidy, homologous recombination defects, tumor ploidy, SNV neoantigens, nonsilent mutation rate, and silent mutation rate, revealed a positive correlation in some cancers." (PMID 40084262, 2025). "Decreased FUT1 is correlated with low EGFR-TKI responsiveness, poor prognosis and tumor metastasis of NSCLC." (PMID 37256139, 2023). "Although the function of FUT9 in tumors not perfectly clear, a previous study showed that suppression of its two gene family orthologs, FUT1 and FUT4, greatly impeded the tumor development, suggesting a potential oncogenic role of this gene." (PMID 35939448, 2022). "In that study, we found that miR-490-3p acted as a tumor-suppressive miRNA in CRC cells, and expression of its gene targets (IRAK1, FUT1, and GPRIN2) was significantly predictive of 5-year overall survival in CRC patients." (PMID 36232922, 2022). "In cells harvested from xenografted tumor of T47D and MCF7, silencing of FUT2 or FUT1 similarly reduced mammosphere formation by 75% and 65%, respectively, as compared to that in shLuc control." (PMID 30854233, 2019). "Tumor growth rates in T47D and MCF7 xenografts were significantly decreased by 65% and 70%, respectively, upon FUT1 knockdown." (PMID 30854233, 2019). "After tail vein injection of these cells into NOD/SCID mice, FUT1 and FUT2 overexpression enhanced tumor localization in the lungs by 2.56 fold and 5.3 fold, respectively of vector control cells as determined by luciferase luminescence." (PMID 30854233, 2019). "We examined the mRNA expression levels of the FUT1, FUT2, B3GALT5 and ST3GAL2 in tumor specimens of 135 HCC patients by qRT-PCR." (PMID 28883415, 2017).
tumor (continued). "The expression levels of FUT1 were significantly correlated with TNM stage (P = 0.002), tumor number (P = 0.001), vascular invasion (P = 0.039), metastasis (P = 0.011) and relapse (P = 0.008)." (PMID 28883415, 2017). "Therefore, we inserted the Fut1 gene and the N-acetylgalactosamine transferase gene into the lentiviral expression vector with the expectation that the lentivirus could efficiently express the blood group A antigen on the cell membrane after the infection of tumour cells." (PMID 34376742, 2021). "In short, both FUT1 and FUT2 are important for tumor growth in vitro and in vivo." (PMID 30854233, 2019). "FUT1, FUT2, B3GNT2, GCNT2, and ST8SIA5 are involved in the blood group biosynthesis, a synthesis of blood group antigens process, which are glycan structures on cell surfaces that can influence tumour cell interactions with the TME, including immune system components." (PMID 39457550, 2024). "As an example, the suppression of the expression of fucosyltransferases FUT1 and FUT4 reduces the synthesis of Ley, which is expressed at the cell surface and involved in several physiological and pathological processes, and it results in inhibition of tumor development." (PMID 35943155, 2022). "This contrasts with studies reporting elevated serum FUT1 levels, which could be attributed to differences between mRNA and protein expression, as well as the potential secretion of FUT1 into the extracellular matrix or bloodstream, reflecting systemic changes rather than localized tumor expression." (PMID 40084262, 2025).
infection (49 papers, 2009 to 2026). The state of being infected such as from the introduction of a foreign agent such as serum, vaccine, antigenic substance or organism. "In this experimental model, in order to reduce the number of animals, piglets were chosen after polymorphism analysis of the FUT1 gene, correlated with F18 receptor expression, susceptible to infection with E. coli O138." (PMID 34438872, 2021). "A 24-fold increase in FUT1 mRNA levels after 72 hours of infection was confirmed by qPCR analysis." (PMID 22590687, 2012). "The higher expression of FUT1 and FUT2 was detected within 2 h post-infection." (PMID 33557187, 2021). "In conclusion, we investigated the changes in fucosylated glycans and FUTs in GES-1 cells infected with H. pylori strains from different sources, and our data demonstrate for the first time that the higher levels of expression of FUT1 and FUT2 were detected within 2 h post-infection." (PMID 33557187, 2021).